POPDC1 (popeye domain cAMP effector 1)
Diseases named in the same sentence as POPDC1 in open-access papers (continued):
Sharing a sentence is not in itself a finding about the gene and the disease.
breast carcinoma (continued). "Interestingly, POPDC1 was significantly suppressed in the more aggressive breast cancer subtypes, MDA231 triple-negative cells and SKBR3 HER2+ cells, in comparison with non-malignant MCF10A cells." (PMID 28954821, 2017). "We hypothesize that suppression of POPDC1 expression in breast cancer cells prevents the POPDC1 functioning at the cell membrane." (PMID 28954821, 2017). "It remains to be established whether POPDC1 is dysregulated in breast cancer, and whether overcoming the dysregulation of POPDC1 could present a potential therapeutic strategy to inhibit breast tumorigenesis." (PMID 28954821, 2017). "Furthermore, functional suppression of POPDC1 promoted breast cancer cell migration and proliferation, which were inhibited by POPDC1 overexpression." (PMID 28954821, 2017). "Overexpression of POPDC1 inhibits breast cancer cell migration and proliferation." (PMID 28954821, 2017). "Hence, we next asked if the POPDC1 suppression attenuates cAMP-mediated breast cancer cell migration and proliferation in these cell lines." (PMID 28954821, 2017). "This dataset suggests that suppression of POPDC1 promotes cell migration and proliferation in breast cancer cells and further supports the hypothesis that dysregulation of POPDC1 promotes a more malignant phenotype in breast cancer." (PMID 28954821, 2017). "Suppression of POPDC1 promotes breast cancer cell migration and proliferation." (PMID 28954821, 2017). "Finally, cAMP interacts with POPDC1 and up-regulates its expression in breast cancer cells." (PMID 28954821, 2017). "However, it remains to be established whether cAMP regulates POPDC1 in breast cancer, and whether POPDC1 is involved in cAMP-mediated inhibition of cell migration, invasion and tumour growth." (PMID 28954821, 2017). "Cell membrane expression of POPDC1 is significantly reduced in MDA231 cells and SKBR3 cells suggesting that the membrane localization of POPDC1 is reduced in triple negative and HER2+ breast cancer cells." (PMID 28954821, 2017). "The present study has further shown that cAMP interacts with POPDC1 and up-regulates its expression in MCF7, MDA231 and SKBR3 breast cancer cells." (PMID 28954821, 2017). "Here we assess the potential of Popeye domain-containing protein 1 (POPDC1) (also known as blood vessel epicardial substance (BVES)), as a novel target for inhibiting cell migration and proliferation in breast cancer." (PMID 28954821, 2017). "We assessed if POPDC1 was suppressed in breast cancer cells in comparison with non-malignant breast cells." (PMID 28954821, 2017). "Additionally, the overexpression of POPDC1 reverts cells to a less malignant phenotype by significantly inhibiting cell migration and proliferation in MCF7, MDA231 and SKBR3 breast cancer cells." (PMID 28954821, 2017). "We postulate that the absence of functional POPDC1 dimers on breast cancer cell membranes potentially leads to a reduction in POPDC1-mediated tight junction maintenance thereby promoting cell migration." (PMID 28954821, 2017). "The present study has further demonstrated differential POPDC1 localization in breast cancer cells in comparison with non-malignant breast cells." (PMID 28954821, 2017). "The interaction between POPDC1 and cAMP has not been reported in breast cancer cells." (PMID 28954821, 2017). "In the present study, we have shown that POPDC1 is expressed in breast cells, but the expression is significantly suppressed in aggressive MDA231 and SKBR3 breast cancer cells, in comparison with non-malignant MCF10A breast cells." (PMID 28954821, 2017).
colon cancer (2 papers, 2019). "On the other hand, forced expression of POPDC1 in human colon cancer cells was associated with a recruitment of β-catenin to the plasma membrane." (PMID 31817925, 2019). "Furthermore, POPDC1 has been shown to be downregulated in colon cancer, furthering the claim that POPDC1 is aiding PP2A in its negative regulation of c-Myc." (PMID 31197601, 2019).
colorectal cancer (2 papers, 2017 to 2019). A primary or metastatic malignant neoplasm that affects the colon or rectum. "In addition, loss of POPDC1 has been shown to promote colorectal cancer tumorigenesis via activation of c-Myc regulated networks and activation of Wnt signalling." (PMID 28954821, 2017). "The gain of POPDC1 function also inhibits tumor growth and metastasis of colorectal carcinoma cells." (PMID 31817925, 2019). "Although POPDC1 does not colocalize with E-cadherin in MDCK epithelial cells, POPDC1 has been associated with the regulation of E-cadherin expression in corneal epithelial cells, HCC and colorectal carcinoma cell." (PMID 31817925, 2019).
myocardial ischemia (2 papers, 2013 to 2016). A disorder of cardiac function caused by insufficient blood flow to the muscle tissue of the heart. "The study examined the hypothesis that Popdc1 might be associated with the caveolae and play a role in myocardial ischemia tolerance." (PMID 24066022, 2013). "Furthermore, a reduction in the ability to cope with myocardial ischemia-reperfusion injury was reported for Popdc1 null mutant mice, suggesting a broader role of Popdc1 in response to striated muscle injury." (PMID 27347491, 2016).
colon adenocarcinoma (1 paper, 2019). "Interestingly, POPDC1, POPDC3 and BVES-AS1 have been linked to colon adenocarcinoma." (PMID 31197601, 2019).
dilated cardiomyopathy (1 paper, 2022). Cardiomyopathy which is characterized by dilation and contractile dysfunction of the left and right ventricles. "Interestingly, the binding site for PDE4 on POPDC1 (R172-K178) contains the residue arginine 172 which is mutated to histidine in a family presenting with dilated cardiomyopathy (DCM)." (PMID 34999055, 2022).
ischemia (1 paper, 2013). A hypoperfusion of the BLOOD through an organ or tissue caused by a PATHOLOGIC CONSTRICTION or obstruction of its BLOOD VESSELS, or an absence of BLOOD CIRCULATION. "The inferior functional recovery and greater infarct size in the Popdc1-null hearts provided clear evidence that this protein plays a role in the response to ischemia or in the recovery process." (PMID 24066022, 2013).
long QT syndrome (1 paper, 2024). "Interestingly, two genome-wide association studies have identified several single nucleotide polymorphisms that affect the expression level of POPDC1 and possibly are associated with human long QT syndrome." (PMID 38540339, 2024).
sick sinus syndrome (1 paper, 2021). A constellation of signs and symptoms which may include syncope, fatigue, dizziness, and alternating periods of bradycardia and atrial tachycardia, which is caused by sinoatrial node dysfunction. "SAN dysfunction in Popdc1 and Popdc2 null mutants is reminiscent of sick sinus syndrome (SSS) in patients." (PMID 34940515, 2021).
cancer (15 papers, 2011 to 2022). A tumor composed of atypical neoplastic, often pleomorphic cells that invade other tissues. "Consistent with POPDC1 being a tumor suppressor, the loss of POPDC1 has been shown to promote cell migration, invasion and metastasis in various cancer types." (PMID 31817925, 2019). "Loss of POPDC1 expression has been shown to not only promote malignant behaviour in cancer, but also promote cardiac and skeletal muscle pathologies, which are inhibited or partially reversed by gain of POPDC1 function." (PMID 28954821, 2017). "Loss of POPDC1 expression has been correlated with enhanced cancer cell proliferation, migration, invasion, metastasis, drug resistance and poor patient survival in various human cancers." (PMID 28954821, 2017). "Since PKA and EPAC, which are also downstream effectors of cAMP, make these effects stronger, this suggests that the pro-apoptotic effects of boosted cAMP in cancer cells could be caused, at least in part, by the actions of POPDC1 proteins." (PMID 35805104, 2022). "In several cancer types, gain of Netrin 1 expression has been observed, which may lead to tumour progression and possibly is associated with the suppression of POPDC1 expression." (PMID 28939104, 2017). "First, the hypermethylation of the POPDC1 gene promoter’s cytosine–phosphate–guanine islands has been seen in a variety of tumors and has been proposed as a biomarker for early cancer detection." (PMID 35805104, 2022). "The known effects of POPDC1 on cancer cell targets will be discussed briefly in the following paragraph." (PMID 35805104, 2022). "POPDC1 is thought to have a tumor suppressor function and decreased POPDC1 expression due to DNA methylation occurs in the early stages of a number of cancers [reviewed:]." (PMID 33261556, 2020). "In cancer, the tumor suppressor functions of POPDC1 are reduced due to protein suppression and mislocalization of the protein to the cytoplasm and nuclear membrane." (PMID 31817925, 2019). "This is further corroborated by the observed suppression of POPDC1 and ZO-1 in various types of cancer cells, consistent with the notion that POPDC1 is a tumor suppressor whose suppression as is the case in some cancer cells enhances cell proliferation." (PMID 31817925, 2019). "Suppression of Popeye domain-containing protein 1 (POPDC1) is known to promote tumorigenesis and correlate to poor clinical outcomes in various cancers, and also promotes cardiac and skeletal muscle pathologies." (PMID 28954821, 2017). "An investigation of pan-cancer hypermethylated CpG sites identified an enhancer, which is hypermethylated in at least 11 different cancer forms and is predicted to regulate POPDC1 expression." (PMID 28939104, 2017). "Secondly, the reduced expression of POPDC1 consistently correlates to tumorigenesis in various cancers and to the promotion of cardiovascular and muscular pathologies." (PMID 28954821, 2017). "Although the exact functional mechanisms of POPDC1 are poorly understood, the known roles and correlations between POPDC1 with cancer and cardiovascular diseases have been recently reviewed." (PMID 28954821, 2017). "Suppression of POPDC1 has been shown to promote cell migration, proliferation and invasion in various human cancer cells and tumour multiplicity in mice." (PMID 28954821, 2017). "POPDC1 proteins have been shown to be downregulated in a variety of cancer cell types." (PMID 35805104, 2022). "POPDC1 and POPDC3 likely function as tumor suppressors and the reported inverse relationship between POPDC1 levels and c-Myc expression and Wnt signaling may link POPDC1 underexpression to intestinal stem cell programming and malignant tumor growth." (PMID 34069715, 2021). "In contrast to POPDC1, POPDC2 and POPDC3, have been associated with both oncogenic and tumor suppressor roles in different cancer types suggesting that these proteins might serve tissue-specific functions." (PMID 31817925, 2019).
cancer (continued). "Moreover, downregulation of POPDC1 and POPDC3 expression in different cancer types has been associated with poor prognosis." (PMID 31817925, 2019). "This suggests that the roles of POPDC2 and POPDC3 might differ in different cancers while POPDC1 potentially regulates cell proliferation in a similar manner in different tissues." (PMID 31817925, 2019). "Furthermore, the application of cAMP to cancer cell lines was found to upregulate expression of POPDC1, which led to the inhibition of cell migration and survival." (PMID 31197601, 2019). "This novel role of POPDC1 could turn out to be critical for the development of novel therapies for cancer patients." (PMID 31197601, 2019). "Suppression of POPDC1 at protein and mRNA level has been observed in various cancers." (PMID 28954821, 2017). "Besides, POPDC1 modulates cell shape and motility as well as vesicle trafficking that may also contribute to cancer cell transformation and tumor progression." (PMID 34069715, 2021). "Indeed, the findings from these studies support the hypothesis that POPDC1 is a tumor suppressor of multiple cancer types." (PMID 31817925, 2019). "Furthermore, POPDC1 has been shown to affect cell proliferation in various cancer types." (PMID 31817925, 2019). "Significantly, expression and phosphorylation levels of LRP6 are increased in Popdc1 null mutants, and are thought to enhance canonical WNT signalling, which is a strong driver of cancer development." (PMID 31197601, 2019). "Suppression of POPDC1 or POPDC3 expression correlates strongly with disease progression and poor clinical prognosis in different cancer forms including gastric cancer, lung cancer, hepatocellular carcinoma, breast cancer and colorectal cancer." (PMID 28939104, 2017). "However, it has not been proven that POPDC1 is in cancer cells or that it interacts with these proteins." (PMID 35805104, 2022). "Unlike its isoform POPDC1 which acts as a tumor suppressor, POPDC3 has been found to play distinct roles in different cancer types." (PMID 34432380, 2021). "Similar results were recently obtained in patients with gastric cancer, which showed a strong correlation between a reduction in the transcript levels of POPDC1 and POPDC3 and the transition from premalignant to a malignant state, while POPDC2 expression levels were independent of the cancer state." (PMID 34940515, 2021).
tumor (15 papers, 2011 to 2025). "In several of these tumours POPDC1 is hypermethylated, which causes a reduction in its expression level." (PMID 31197601, 2019). "Analysis of fresh tumor tissue lysates revealed the mRNA levels of POPDC1 and POPDC2 remained unchanged, but there was a substantial upregulation in POPDC3 mRNA and protein levels in POPDC3-OE priNSCLC-1 xenografts." (PMID 39971925, 2025). "The association of POPDC1 and POPDC3 downregulation with IM and GC suggests a role in tumor suppression and highlights them as potential biomarkers for IM and GC progression and as prospective treatment targets." (PMID 34069715, 2021). "The association of POPDC1 and POPDC3 downregulation with IM-to-GC transition implicates a role in tumor suppression and highlights them as potential biomarkers for GC progression and prospective treatment targets." (PMID 34069715, 2021). "Studies on POPDC1 (BVES), the prototype of the POPDC family, have provided insights as to mechanisms through which POPDC1 silencing or suppression facilitate tumor development and progression." (PMID 34069715, 2021). "We found inverse correlation between the expression of mucins that characterize severity of malignant transformation, and the tumor suppressors POPDC1 and POPDC3, suggesting an inverse regulatory linkage." (PMID 34069715, 2021). "This gives further support to the hypothesis that POPDC1 is a tumor suppressor whose high expression and function inhibits malignant behavior such as the initiation of cell migration, while its loss of function promotes a migratory and malignant phenotype in tumor cells." (PMID 31817925, 2019). "POPDC1 is thought to function as a tumor suppressor that inhibits or regulates cell proliferation in normal physiology." (PMID 31817925, 2019). "We postulate that the function of POPDC1 as a tumor suppressor is primarily dependent on its proper plasma membrane localization." (PMID 31817925, 2019). "POPDC1 (also known as BVES), is a transmembrane protein encoded by the POPDC1 gene and is thought to be a tumour suppressor that is dysregulated to promote malignant cell behaviour." (PMID 28954821, 2017). "Significant reductions in expression of POPDC1 have also been identified in multiple tumour types." (PMID 31197601, 2019). "The molecular mechanisms of how a reduction in POPDC1 expression promotes malignant tumour growth is still unknown." (PMID 31197601, 2019). "Interestingly, a gain of POPDC1 function in tumor cells inhibits cell proliferation, migration and invasion thereby reducing malignancy." (PMID 31817925, 2019). "Here, POPDC1 plays a role as a tumour suppressor by limiting c-Myc and WNT signalling." (PMID 31197601, 2019). "The reduction in Popdc1 expression in the tumour is probably due to an increase in methylation." (PMID 28939104, 2017). "In addition to the essential roles that POPDC proteins play in the maintenance of structure and function of skeletal muscles and in cardiac pacemaking and conduction, POPDC1 may play a role in tumor formation." (PMID 33261556, 2020). "Indeed POPDC1 is now thought of as a tumour suppressor gene." (PMID 31197601, 2019). "The interaction between POPDC1, a tumor suppressor, and one of the main tumor suppressor phosphatases in mammalian cells could thus imply an effective anti-proliferative collaboration that might be relevant in regulating cell proliferation in multiple cell lines and tumors." (PMID 31817925, 2019). "Analysis of fresh tumor tissue lysates revealed substantial reductions in POPDC3 mRNA and protein levels in sh-POPDC3 xenografts, while the mRNA levels of POPDC1 and POPDC2 remained unchanged." (PMID 39971925, 2025).
bacterial infection (1 paper, 2021). "The silencing of POPDC1 in HEK293T cells increased their susceptibility to infection with enteropathogenic bacteria similar to the increased sensitivity of colonic endothelial cells to bacterial infection in POPDC1 null mice." (PMID 34069715, 2021).
POPDC1 also shares sentences with these, for which no sentence is quoted: cardiac disease (3 papers); Fallot's tetralogy (2); meningioma (2); Arrhythmia (1); breast tumours (1); cardiovascular diseases (1); gallbladder cancer (1); glioblastoma (1); glioma (1); infection (1); pancreatic cancer (1); pericardial effusion (1); stenosis (1); uveal melanoma (1).